IDH1 (isocitrate dehydrogenase (NADP(+)) 1)
Diseases named in the same sentence as IDH1 in open-access papers (continued):
Sharing a sentence is not in itself a finding about the gene and the disease.
glioma (continued). "Recently, the World Health Organization (WHO) added the presence of one of the recurrent point mutations in the isocitrate dehydrogenase genes (IDH1 or IDH2) and co-deletion of chromosomal arms 1p/19q to the glioma diagnosis criteria." (PMID 33926464, 2021). "In general, there appears to be experimental agreement that gliomas with mutIDH1RR132H are less glycolytic and rely more on oxidative phosphorylation than WT IDH1 gliomas." (PMID 35028610, 2021). "They showed that monocytes/macrophages constitute one-quarter of the myeloid immune infiltrate in IDH1-wt gliomas and one-half in brain metastases, but they are rare in human IDH-mut gliomas." (PMID 33809675, 2021). "Somatic mutations, such as R132H in IDH1 and R140Q or R172H in IDH2 have been found in various types of human cancers, including AML, glioma, chondrosarcoma and so on." (PMID 34425876, 2021). "Through inducing anti-tumor immunity, a peptide vaccine targeting mutant IDH1 had been proved to be a feasible new strategy for the treatment of IDH1 (R132H) mutant gliomas in recent days." (PMID 34404444, 2021). "Somatic point mutations in IDH1 and IDH2 genes have been found in glioma, glioblastoma multiforme (GBM) and acute myeloid leukemia (AML), prevalently concentrated in specific hot spots." (PMID 34065551, 2021). "A phase 1 clinical trial provides evidence that a vaccine against mutant IDH1 is safe and produces a T helper immune response in patients with glioma." (PMID 33762734, 2021). "Mutations in IDH1 occur in the vast majority of low-grade gliomas (WHO I–II) and secondary high-grade gliomas." (PMID 34490090, 2021). "In the present study, we aim to assess the relationship of combined IDH1 mutation status and anatomical tumor-SVZ distance to clinical features of patients with glioma." (PMID 34490090, 2021). "Gliomas patients harboring IDH mutations, including IDH1 and IDH2 mutation, have a better prognosis than the wild type." (PMID 34961815, 2021). "The results revealed the positive correlation between the tumor-SVZ distance and two parameters (OS and PFS) except PFS of patients with IDH1-wild glioma." (PMID 34490090, 2021). "On the contrary, a previous AFM indentation study found IDH1-R132C-mutant WHO grade II and III gliomas to be softer than IDH1-wildtype ones." (PMID 34572766, 2021). "A similar role for Notch1 activation was also observed in isocitrate dehydrogenase 1 (IDH1) mutant diffuse low-grade gliomas." (PMID 34771555, 2021). "Although IDH1 mutation has dual effects, acting either as an oncogene or as a tumor suppressor gene in glioma, patients with IDH mutation exhibited better prognosis than those with wild-type IDH1." (PMID 34584069, 2021). "It has been recently reported that tryptophan catabolism is a key modulator of immune suppression in mutant IDH1 (mIDH1) gliomas." (PMID 34203535, 2021). "We concluded that BCAT1 is a strong prognostic factor for glioma patients and involved in the malignant progression of IDH1 wild-type gliomas." (PMID 33493139, 2021).
glioma (continued). "Branched-chain amino acid transaminase 1 (BCAT1), which is located in the cytosol and widely expressed in the brain, is present at significantly lower levels in mutIDH1R132H glioma PTB and PDX compared with WT IDH1 glioma samples." (PMID 35028610, 2021). "We studied the predictive efficacy of multiple dMRI parameters for glioma IDH1 genotype and cell proliferation and found their great potential." (PMID 34880724, 2021). "Treatment with GLS inhibitors showed a greater reduction in viability for mutIDH1 compared with WT IDH1 glioma and AML cells." (PMID 35028610, 2021). "In concordance with Pan Glioma RNA Expression Cluster specificity, all IDH1 mutant samples were assigned to the LGr1 or LGr3 RNA clusters, even though they were split on the dendrogram into DA and GB specific clusters." (PMID 34131149, 2021). "Gliomas harboring mutant IDH1 display high levels of DNA hypermethylation in CpG rich domains, which are associated with increased tumor progression and altered gene expression." (PMID 34168976, 2021). "At the same time, we verified the expression levels and status of well-known molecular markers including MGMT promoter methylation, IDH1 mutant, and co-deletion of 1p19q in low-grade glioma patients (WHOII, WHOIII) between high and low expression of SYP." (PMID 34136394, 2021). "The ALPS index of IDH1 mutant gliomas was significantly higher than that of IDH1 wild-type gliomas (p < 0.001)." (PMID 34631582, 2021). "An MRS study of individuals with mutIDH1R132H and mutIDH2R172K (grade II and III glioma) reported increased lactate compared with WT IDH1/2 gliomas." (PMID 35028610, 2021). "CNS-invading leukocytes in the IDH1-mut gliomas were predominantly composed of monocytes and lower frequencies of macrophages." (PMID 33809675, 2021). "The ALPS index of IDH1 wild-type gliomas was significantly lower than that of IDH1 mutant gliomas (p < 0.001)." (PMID 34631582, 2021). "Then, we divided the non-SVZ-contacting glioma into two groups: IDH1-wild glioma and IDH1-mut glioma." (PMID 34490090, 2021). "Among patients with SVZ-negative glioma, there was a positive association of IDH1 mutation with OS (p = 0.007) and PFS (p = 0.007) by contrast to wild-type IDH1." (PMID 34490090, 2021). "Through bioinformatic analysis of more than 45,000 human pan-cancer samples from three independent datasets, we show here that IDH1 mutations are rare events in human cancer but are exclusively prevalent in WHO grade II and grade III (lower-grade) glioma." (PMID 34440884, 2021). "Looking further in energy metabolism, it has been shown that a mutation in IDH1/2 genes inhibits isocitrate dehydrogenase activity and correlates with decreased NAA and NAAG levels in gliomas." (PMID 34573036, 2021). "In a word, with the increase of pathological grade, the tumor microstructure is more complex, with higher cell density and more disturbed water molecule movement, but IDH1 gene phenotype will affect the development of gliomas at a microscopic point of view." (PMID 34880724, 2021). "While the exact mechanisms connecting this cellular activity to gliomagenesis are not yet completely understood, IDH1/2mut gliomas are generally much less aggressive than their IDH1/2 wild-type (IDHwt) counterparts." (PMID 34424450, 2021). "Based on the large-scale sample collection, we analyzed the gene expression pattern of BCAT1 in glioma tissues as well as its relationship with IDH1 status and other clinical features." (PMID 33493139, 2021). "Mutant IDH1 is considered a metabolic marker of secondary GBM because of its ubiquitous expression in lower-grade gliomas that eventually progress to GBM." (PMID 34361055, 2021).
glioma (continued). "The enrichment of immature CD56int/bright was found in CD16− NK cells among lymphocytes in the IDH1-wt gliomas, whereas predominantly CD56int/brightCD16+ NK cells accumulated in the IDH1-mut gliomas." (PMID 34571910, 2021). "Consistent with this, point mutation of Isocitrate Dehydrogenase 1 (IDH1) (R132H), which is frequently found to be coincident with ATRX mutations in certain cancers, including glioma, is sufficient to create tumorigenic cells with ALT characteristics." (PMID 34828344, 2021). "Mutations in the NADPH-linked mitochondrial isoforms of IDH1 and IDH2 have led to impaired energy production in the mitochondria and thus, provide clear evidence for mitochondrial dysfunction in gliomas." (PMID 33802571, 2021). "The negatively related IDH1-mutation in LGG and co-deletion of 1p19q in whole grade glioma, have been previously associated with prolonged PFS and OS in patients after treatment." (PMID 34123793, 2021). "Silencing the LDHB gene with small interfering RNA has been shown to reduce cell growth in a number of cancer cell lines, including WT IDH1 glioma." (PMID 35028610, 2021). "To this end, we investigated three orthotopic mutant IDH1 glioma mouse models and studied the effects of two brain penetrant mutant IDH inhibitors, AG-881 and BAY-1436032, that are currently in clinical trials for glioma patients." (PMID 33668509, 2021). "To investigate how B7H3 was degraded in IDH mutant glioma cells, we screened U87 cells and IDH1-R132H U87 cells with several inhibitors by targeting intracellular protein-degradation pathways." (PMID 34079802, 2021). "Recurrent IDH1 point mutations, which have been identified as contributors to gliomagenesis, is used to classify gliomas and represents a major division of mutant IDH1 gliomas from wild-type-IDH1 (wt-IDH1) gliomas." (PMID 34422657, 2021). "Further, performance of each parameter was compared for glioma grading under the same IDH1 genotype." (PMID 34880724, 2021). "IDH1 and IDH2 genes encode isocitrate dehydrogenase 1 (IDH1) and isocitrate dehydrogenase 2 (IDH2) in gliomas." (PMID 34961815, 2021). "The results revealed that B2M expression was positively correlated with glioma grade and remarkably varied in different IDH1 status groups." (PMID 33960680, 2021). "Mutated IDH1 thus blocks PI3K/Akt signaling, a pathway associated with the development of a more aggressive glioma phenotype." (PMID 34070746, 2021). "Mutations in the IDH1 and IDH2 genes are well described in lower-grade gliomas (grade II and III astrocytomas and oligodendrogliomas) and secondary glioblastomas, where they have an incidence of more than 70 %." (PMID 34641967, 2021). "The remaining 18% (14/80) were reclassified as glioma (NOS) given their IDH1/2 WT, CIC WT, and FUBP1 WT status." (PMID 33778493, 2021). "Specifically, our work discovers the potential role of cellularity in tumor histopathology image and IDH1/2 mutation status for grading stratification within lower grade (grade II and III) gliomas." (PMID 34277415, 2021). "Of particular note, the significance of 1p/19q codeletion and mutation of isocitrate dehydrogenase 1 or 2 (IDH1-mt or IDH2-mt) has recently been established with regard to the prediction of the prognosis of gliomas." (PMID 34513462, 2021). "The variables that increased the probability of short-term glioma recurrent risk included older age at diagnosis, lower preoperative KPS, high-grade tumor, PR, and IDH1 wild type." (PMID 34778058, 2021). "IDH1 wild-type gliomas display a more immunosuppressive tumor microenvironment including a more prominent immune cell infiltration and higher PD-L1 expression." (PMID 33493139, 2021).
glioma (continued). "Distinct epigenetic profiles have been recognized in gliomas based on DNA methylation and, in combination with other somatic alterations, characterized clinically relevant subtypes: H3 K27, G34, IDH1, RTKI, RTKII, and mesenchymal." (PMID 34496929, 2021). "Differential fluorescence upon 5-ALA treatment was observed in the IDH1R132H mutant compared to IDH1 wild-type (WT) WHO grade III gliomas." (PMID 33540759, 2021). "This implies that IDH1 wild type effect on genomic instability can be used to improve the clinical prognosis of low-grade gliomas." (PMID 34081618, 2021). "Glioma cells overexpressing IDH1-R132H displayed higher chemosensitivity due to increased generation of reactive oxygen species (ROS) and depletion of glutathione, suggesting that they respond better to chemotherapy than IDH1-wt gliomas." (PMID 34070746, 2021). "A preclinical study using WT IDH1 stem-like glioma cells demonstrated that treatment with chloroquine during radiation significantly increased cell death; however, in this context, it was considered to be due to the autophagy inhibitory effects of chloroquine." (PMID 35028610, 2021). "IDH1 and IDH2 are mutated in >70% of lower-grade gliomas (grades II and III), in some glioblastomas, and ∼20% of AML, but also in cholangiocarcinoma, chondrosarcoma, and in other cases of different tumor types." (PMID 33572577, 2021). "IDH1 status was known only in U87 cell line (wild type); in high-grade gliomas, Buckingham has shown high levels of glutamate release by tumor cells in an experimental model of brain tumor-associated epilepsy." (PMID 34068749, 2021). "Instead of catalysis of isocitrate to α-ketoglutarate in the Krebs cycle, in IDH1-mutant glioma cells, D-2-hydroxyglutarate (D-2HG) is generated." (PMID 34067762, 2021). "2HG is an oncometabolite, produced in glial tumor cells bearing an isocitrate dehydrogenase (IDH) gene mutation, either IDH1 or IDH2." (PMID 35340697, 2021). "BCAT1 expression was positively correlated with glycolytic enzymes, which are enriched in IDH1 wild-type gliomas and related to poor overall survival of glioma patients." (PMID 33493139, 2021). "The presence of astrocyte-like SOX9+ and oligodendrocyte-like OLIG1+ cells in grade II IDH1-mutant gliomas raises new questions about their role in the pathology." (PMID 33925547, 2021). "With the development of sequencing technology, IDH1 or IDH2 mutations have been found in various malignant tumors, such as AML, glioma, chondrosarcoma." (PMID 33981605, 2021). "In IDH1-mutant gliomas it has been suggested that 2-HG generation is responsible for the presence of G-CIMP, likely due to reduced TET demethylase activity." (PMID 33842321, 2021). "In this study, there were 42 patients with IDH1-mutant glioma and 49 patients with IDH1 wild-type glioma." (PMID 34880724, 2021). "IDH1 mutations are predominately found in WHO grade II and III gliomas (70% of cases) compared to grade IV GBM (12% of cases), and GBM which harbor the IDH1 mutation lead to significantly longer survival times of greater than two-fold." (PMID 34685601, 2021). "In 2016, the World Health Organization classified levels of Central Nervous System tumors based on molecular features, specifically the isocitrate dehydrogenase 1 (IDH1) genotype." (PMID 34880724, 2021). "Apoptosis of the human glioma cells containing IDH1-R132H can be considered as a tumor suppressor by downregulating Wnt/β-catenin signaling." (PMID 33221817, 2020). "The median FLT T/N ratio in IDH1-mutant and IDH1-wildtype gliomas were 4.18 (IQR 2.28–6.39) and 14.7 (8.98–20.38), respectively." (PMID 32382870, 2020). "We found IDH1 mutant glioma were inclined to cross the midline to the other hemisphere and were more likely to exhibit homogeneous signal intensity as well as less contrast enhancement." (PMID 32582544, 2020).
glioma (continued). "IDH1 and IDH2 mutations also frequently occur in for instance acute myeloid leukaemia (AML), glioma and cholangiocarcinoma." (PMID 31728625, 2020). "The expression of ACAA2 in IDH1 wild-type glioma was significantly higher than that in IDH1 mutant glioma, while participating in fatty acid beta." (PMID 32280672, 2020). "Mutant IDH1 is a metabolic marker of secondary glioblastoma because of its ubiquitous expression in lower grade gliomas that eventually progress to glioblastoma." (PMID 33614476, 2020). "In the current study, we found a significant correlation between MGMT promoter methylation and IDH1 status in glioma cases (p = 0.03)." (PMID 33552543, 2020). "A total of 33 lncRNAs were found to be differentially expressed in all three independent datasets, including 21 lncRNA genes that were upregulated and 12 lncRNA genes that were downregulated in IDH1 mutant glioma." (PMID 33329315, 2020). "Mutant IDH1 (IDH1mut) gliomas are considered good candidates for targeting this pathway because of the contribution of glutamine to their newly acquired function: synthesis of 2-hydroxyglutarate (2HG)." (PMID 33101674, 2020). "Isocitrate Dehydrogenase mutations, IDH1, and IDH2 have been found in gliomas, and classifying gliomas based on their molecular profiling of IDH status (mutated vs. wild-type) creates clinically distinct groups." (PMID 32111869, 2020). "Other studies also show that FTO functions as an oncogenic role via maintaining the stability of transcripts of avian myelocytomatosis viral oncogene homolog (c-Myc) and CCAAT enhancer binding protein alpha (CEBPA) in glioma, especially IDH1/2 mutant glioma." (PMID 32244981, 2020). "IDH1 status was increasingly recognized as the crucial genetic marker for glioma patients and had been included in the 2016 WHO classification of glioma." (PMID 33229627, 2020). "For the grade IV glioma group, Indians were found to have the highest incidence of positive results for two of the biomarkers: MGMT promoter methylation (50%) and IDH1 mutation (30%)." (PMID 32005184, 2020). "In 2008, compelling research showed that mutations in isocitrate dehydrogenase (IDH1 and IDH2) are frequently identified in the World Health Organization (WHO) grade II/III gliomas and secondary glioblastomas (GBMs)." (PMID 32825279, 2020). "Mutations in the IDH1 and IDH2 genes are found in multiple hematologic and solid tumors, including acute myeloid leukemia (AML) and glioma." (PMID 31028664, 2020). "In this study, the upregulated CSF sPD-L1 levels tended to occur in the glioma patients with wild-type IDH-1 or maintained 1p/19q." (PMID 32038986, 2020). "Mutant IDH1 glioma tumors, which are less aggressive than wild-type IDH1 tumors, have low TAN infiltration." (PMID 32182988, 2020). "This new classification emphasized the essential role of molecular testing in tailoring clinical decision and predicting patients’ survival, in which IDH1 and 1p/19q status play an especially central role to classify the glioma tumors." (PMID 32957941, 2020). "The PD-L1 inhibitor pembrolizumab (MK-3475) is being evaluated in a clinical trial of patients with recurrent IDH1-mutant grade II–IV gliomas whose tumours have a hypermutator phenotype (NCT02658279)." (PMID 32291392, 2020).